ZFAS1 (ZNFX1 antisense RNA 1)
Diseases named in the same sentence as ZFAS1 in open-access papers (continued):
Sharing a sentence is not in itself a finding about the gene and the disease.
osteosarcoma (continued). "The role of ZFAS1 in osteosarcoma is investigated in this study." (PMID 35184675, 2022). "In addition, Kaplan-Meier analysis showed that a higher level of ZFAS1 indicated significantly shorter overall survival of osteosarcoma patients." (PMID 35184675, 2022). "We found that the expression of ZFAS1 was increased in osteosarcoma clinical tissues." (PMID 35184675, 2022). "The influence of ZFAS1 on osteosarcoma cells metastasis was further investigated." (PMID 35184675, 2022). "Through BMI1 and ZEB2, ZFAS1 regulates osteosarcoma cell growth and metastasis." (PMID 35184675, 2022). "Several studies have found that ZFAS1 promotes osteosarcoma via ceRNA mechanisms." (PMID 35184675, 2022). "Our study provides novel insight into the role of ZFAS1 in osteosarcoma." (PMID 35184675, 2022). "The following experiment elucidated the role of ZFAS1 promoted osteosarcoma progression in vivo." (PMID 35184675, 2022). "ZFAS1 was shown to play the same role in osteosarcoma and papillary thyroid carcinoma." (PMID 34552050, 2021). "In addition, the high expression of ZFAS1 in osteosarcoma was reported to function as a tumorigenic lncRNA, indicating the promotion of cell growth and metastasis." (PMID 32744323, 2020). "Additionally, lncRNAs ZFAS1 sponges miR-486 to promote osteosarcoma cells metastasis and progression." (PMID 31781561, 2019). "In conclusion, our data elucidated the regulatory function of lncRNA ZFAS1 in the development and progression of osteosarcoma via acting as competing endogenous RNA (ceRNA) of miR-486, suggesting an effective therapeutic strategy for osteosarcoma treatment." (PMID 29262629, 2017). "ZFAS1 is a novel identified lncRNA, however, its role in osteosarcoma is still unclear." (PMID 29262629, 2017). "Moreover, the over-expressed ZFAS1 was closely correlated with poor prognosis of osteosarcoma patients." (PMID 29262629, 2017). "Furthermore, in 53 pairs of osteosarcoma patient samples, the up-regulated expression of ZFAS1 was closely related to poor prognosis." (PMID 29262629, 2017). "In summary, rescue experiment revealed that miR-486 could rescue the function of ZFAS1 on osteosarcoma progression." (PMID 29262629, 2017). "Rescue experiments confirmed that miR-486 could reverse the functions of ZFAS1 on osteosarcoma genesis." (PMID 29262629, 2017). "Additionally, in osteosarcoma, ZFAS1/miR-135a axis regulates growth and metastasis." (PMID 40109869, 2025). "However, the Lnc-ZFAS1-mediated mechanism in osteosarcoma still remains insufficient." (PMID 36473367, 2023). "Interestingly, we found Lnc-ZFAS1 induced the EMT in osteosarcoma." (PMID 36473367, 2023). "Furthermore, we validated that Lnc-ZFAS1 could sponge miR-520b and miR-520e in osteosarcoma cell lines." (PMID 36473367, 2023). "Moreover, we observed RHOC could act a dispensable role in recovering the impairment of the capacities of proliferation, migration, and invasion, as well as the loss of EMT caused by Lnc-ZFAS1, thereby identifying RHOC as an oncogenic driver in osteosarcoma." (PMID 36473367, 2023). "In addition, depleted Lnc-ZFAS1 restrained osteosarcoma cells proliferation, migration, and invasion, which could be rescued by RHOC overexpression." (PMID 36473367, 2023). "In addition, we evaluated the impact of ZFAS1 on osteosarcoma progression in vivo." (PMID 35184675, 2022). "Thus, we hypothesized that ZFAS1 has the potential to regulate osteosarcoma progression through directly binding to and stabilizing SRSF3." (PMID 35184675, 2022). "Thus, flow cytometry showed that ZFAS1 knockdown could induce cell cycle arrest and promote apoptosis on osteosarcoma cells in vitro." (PMID 29262629, 2017). "To uncover the functional influence of Lnc-ZFAS1 upon osteosarcoma progression, we established Lnc-ZFAS1-upregulated U2OS cells and Lnc-ZFAS1-downregulated KHOS cells." (PMID 36473367, 2023). "First, we examined the expressions of ZFAS1 and SRSF3 in osteosarcoma patients and their relationship to prognosis outcomes." (PMID 35184675, 2022).
osteosarcoma (continued). "The biologic function of ZFAS1 in osteosarcoma cells was explored based on the upregulation of both ZFAS1 and SRSF3 in osteosarcoma." (PMID 35184675, 2022). "Moreover, we revealed the regulatory mechanism between Lnc-ZFAS1 and miR-520b/miR-520e-mediated RHOC and provided a novel clue for ameliorating osteosarcoma." (PMID 36473367, 2023). "Moreover, we identified Lnc-ZFAS1 functionally acted as a sponger of miR-520b and miR-520e to upregulate RHOC in osteosarcoma." (PMID 36473367, 2023). "Further functional experiments revealed that ZFAS1 could stabilize SRSF3 protein, increasing its level in osteosarcoma cells." (PMID 35184675, 2022). "LncRNA microarray assay revealed that lncRNA ZFAS1 was significantly up-regulated in 3 pairs of osteosarcoma and adjacent non-tumor tissue, which was confirmed by RT-PCR." (PMID 29262629, 2017). "RT-PCR showed that ZFAS1 expression was significantly up-regulated in osteosarcoma tissue compared to that of in adjacent non-tumor tissue." (PMID 29262629, 2017). "Lnc-ZFAS1 acted sponger of miR-520b and miR-520e to promote RHOC, indicating that Lnc-ZFAS1/miR-520b/RHOC and Lnc-ZFAS1/miR-520e/RHOC axes might serve as potential therapeutic strategies against osteosarcoma." (PMID 36473367, 2023). "Moreover, the up-regulation of MMP-9, Vimentin and N-cadherin and the downregulation of E-cadherin were observed in Lnc-ZFAS1 overexpressed U2OS cells, and the contrast results were induced by Lnc-ZFAS1 depletion, implying Lnc-ZFAS1’ promotion effect on EMT in osteosarcoma." (PMID 36473367, 2023). "For example, ZNFX1 antisense RNA 1 (ZFAS1) may upregulate the expression of BMI1, a major component of epigenetic repressor PRC1, by competitively binding miR-200b/c, thereby driving tumorigenesis in osteosarcoma." (PMID 32928281, 2020).
colon cancer (12 papers, 2017 to 2023). "ZFAS1 knockdown was associated with decreased cellular proliferation, migration, and invasion in two colon cancer cell lines (HT29 and SW480)." (PMID 33771981, 2021). "The expression of long non-coding RNA ZFAS1 was higher in colon cancer tissue than in normal tissue." (PMID 35682560, 2022). "In this study, we describe the identification and validation of lncRNA ZFAS1 as having an important role in colon cancer progression using a large RNA-seq data set and institutional clinical samples." (PMID 33771981, 2021). "This analysis identified lncRNA ZFAS1 as significantly increased in colon cancer compared to normal colon epithelium." (PMID 33771981, 2021). "Knockdown of ZFAS1 can lead to a less aggressive phenotype in colon cancer cell lines, reduction in the mesenchymal marker vimentin, and an increase in the epithelial marker E-cadherin." (PMID 33771981, 2021). "LncRNA zinc finger antisense 1 (ZFAS1) is overexpressed in colon cancer specimens and correlates with TNM stage, vascular invasion and metastasis." (PMID 33246471, 2020). "LINC00261 overexpression has been demonstrated to promote cell apoptosis, whereas lncRNA ZFAS1 impedes colon cancer cell apoptosis." (PMID 33246471, 2020). "ZFAS1 targeted miR-200b/-c to promote EMT in colon cancer cells." (PMID 35682560, 2022). "In addition, they found knockdown of ZFAS1 impeded proliferation, invasion, and promoted apoptosis of colonic cancer cell lines." (PMID 30186041, 2018). "Moreover, plasma of colon cancer patients has higher levels of ZFAS1." (PMID 33246471, 2020). "Moreover, ZFAS1 overexpression accelerates colon cancer cell proliferation." (PMID 33246471, 2020). "LncRNA ZFAS1 accelerates the EMT process via the induction of ZEB1 expression, while knockdown of ZFAS1 upregulates the expression of E-cadherin and ZO-1, but decreases that of ZEB1, vimentin and N-cadherin in colon cancer cells." (PMID 33246471, 2020). "It is reported that the interaction between CDK1/cyclin B1 complex and ZNFX1 antisense RNA 1 (ZFAS1) leads to cell cycle progression and cell apoptosis suppression in the progression of colon cancer." (PMID 30186855, 2018).
cervical cancer (11 papers, 2020 to 2023). A primary or metastatic malignant neoplasm involving the cervix. "Inhibition of ZFAS1 reduces cervical cancer tumor growth and the expression levels of KLF6 but increases the expression levels of miR-190a-3p." (PMID 35406713, 2022). "Upregulation of lncRNA ZFAS1 was observed in cervical cancer specimens and correlated with poor prognosis." (PMID 36438563, 2022). "ZFAS1 siRNA treatment led to suppression of migration, invasion and growth in cervical cancer cells." (PMID 36438563, 2022). "In cervical cancer, lncRNA ZFAS1 with m6A modification conduces to unfavorable clinical outcome by suppressing miR-647 to lead to tumor metastasis." (PMID 34295922, 2021). "High expression of lncRNA KCNMB2-AS1 is positively correlated with poor prognosis of cervical cancer by upregulating the oncogene IGF2BP3, which in turn increases the stability of KCNMB2-AS1; lncRNA ZFAS1 promotes the metastasis of cervical cancer by suppressing miR-647 mediated by METLL3." (PMID 35432630, 2022). "Moreover, NORAD and ZFAS1 have been reported to promote cell invasion and migration in cervical cancer and bladder cancer, respectively, by up-regulating ZEB2." (PMID 36514044, 2022). "LncRNA ZFAS1 (Zinc finger antisense 1) impacts cervical cancer growth through miR-190a-3p." (PMID 35406713, 2022). "ZFAS1 siRNA also enhanced cisplatin sensitivity in cervical cancer cells and in nude mice." (PMID 36438563, 2022). "Therefore, ZFAS1 could regulate cervical cancer pathogenesis by regulating the miR-190a-3p/KLF6 axis." (PMID 35406713, 2022). "ZFAS1 and its m6A modification may be a promising target for cervical cancer treatment." (PMID 36058934, 2022). "ZFAS1 has been shown to activate MAPK signaling pathway, and promote the migration and invasion of cervical cancer cells by regulating the MAPK/p38 signaling pathway." (PMID 33391210, 2020).
Sepsis (11 papers, 2021 to 2025). Sepsis is defined as life-threatening organ dysfunction caused by a dysregulated host response to infection. "The ZFAS1/Notch signaling pathway is subject to regulation by the transcription factor Sp1, which ameliorates myocardial injury associated with sepsis." (PMID 41041277, 2025). "Acting as a circulating biomarker for sepsis, high plasma levels of the lncRNAzinc finger antisense 1 (ZFAS1) are negatively associated with disease risk,inflammatory levels, and long-term mortality." (PMID 39077015, 2023). "The interplay between apoptosis, autophagy, and pyroptosis, orchestrated by key players such as ZFAS1 and miR-208a-5p, unravels a complex web of regulatory pathways that contribute to myocardial injury in the context of sepsis." (PMID 39062521, 2024). "In LPS-induced SD rats and H9C2 cardiomyocytes, theoverexpression of ZFAS1 ameliorated sepsis-induced cardiomyocyte pyroptosis andmyocardial damage by targeting the miR-138-5p/SESN2 and miR-34b-5p/SIRT axes." (PMID 39077015, 2023). "ZFAS1 has been reported to beinvolved in sepsis-induced multiple organ dysfunction, including acute injury ofthe heart, lung, and kidneys." (PMID 39077015, 2023). "Downregulation of ZFAS1 reduced LPS-induced pyroptosis and enhanced LPS-suppressed autophagy in sepsis-induced cardiac dysfunction." (PMID 34956235, 2021). "Zinc finger antisense 1 (ZFAS1), which is activated by the transcription factor SP1, can induce pyroptosis in cardiomyocytes by targeting the miR-590-3p/AMPK/mTOR signal, and aggravate cardiac dysfunction caused by sepsis." (PMID 37872948, 2023). "Furthermore, ZFAS1 was detected to be downregulated in sepsis patients comparing to normal controls and achieved an Area Under the Receiver Operating Characteristic (AUROC) of 0.814 in sepsis diagnosis." (PMID 33863291, 2021). "However, inhibiting the expression of ZFAS1 could improve cardiac function, suggesting that ZFAS1 aggravates myocardial injuries in sepsis." (PMID 35967871, 2022). "ZFAS1, activated by SP1, aggravates the progression of sepsis-induced cardiac dysfunction via targeting miR-590-3p/AMPK/mTOR signaling-mediated autophagy and pyroptosis of cardiomyocytes." (PMID 40041174, 2025). "Mechanistic insights unveiled that SP1 activated ZFAS1 expression, thereby mediating cardiomyocyte pyroptosis and autophagy through the miR-590-3p/AMPK/mTOR signaling pathway, ultimately exacerbating sepsis-induced cardiac dysfunction." (PMID 39062521, 2024). "SP1 is the positive regulator of ZFAS1 that worsens cardiac dysfunction induced by sepsis, suggesting the involvement of SP1 in sepsis." (PMID 35091534, 2022).
nasopharyngeal carcinoma (9 papers, 2019 to 2024). A carcinoma arising from the nasopharyngeal epithelium. "MiR-150 is the target of lncRNA ZFAS1, which is an independent prognostic factor for nasopharyngeal carcinoma and is closely linked with its metastasis and poor prognosis." (PMID 35847022, 2022). "Nasopharyngeal cancer cells contain high levels of ZNFX1 antisense RNA 1 ZFAS1 and low levels of miR-135a-5p." (PMID 37190145, 2023). "QRT-PCR analysis of ZFAS1 in the nucleus and cytoplasm showed that ZFAS1 was mainly located in the cytoplasm of nasopharyngeal carcinoma cells (p < 0.05)." (PMID 34980191, 2022). "ZFAS1 knockdown suppresses nasopharyngeal cancer cell proliferation by sponging miR-135a-5p." (PMID 37190145, 2023). "Upregulation of lncRNA ZFAS1 has been identified in nasopharyngeal carcinoma and osteosarcoma." (PMID 32515146, 2020). "In addition, the ZFAS1 lncRNA has been shown to promote nasopharyngeal carcinoma progression through activation of the Wnt/β-catenin signaling pathway." (PMID 31065463, 2019). "Therefore, silibinin may inhibit the proliferation of nasopharyngeal cancer cells by regulating the ZFAS1–miR-135a-5p axis." (PMID 37190145, 2023). "ZFAS1 regulates the expression of ATG10 by competitively adsorbing miR-100-3p to promote the proliferation and metastasis of nasopharyngeal carcinoma cells in vivo and in vitro." (PMID 34980191, 2022). "In nasopharyngeal carcinoma (NPC), the lncRNA ZFAS1, whose RNA stability is enhanced by the m6A methyltransferase METTL3, promotes NPC cell proliferation, migration and tumor growth and regulates autophagy levels by modulating the miR-100-3p/ATG10 axis and through the PI3K/AKT pathway." (PMID 38933333, 2024). "Although the targeting site of miR-7-5p on ZFAS1 was validated in nasopharyngeal carcinoma cells, very limited efforts have been made in reporting the role, nor the molecular mechanism of ZFAS1 in ocular diseases." (PMID 36092160, 2022).
atherosclerosis (8 papers, 2019 to 2025). A disease characterized by the build-up of fatty material and calcium deposition in the arterial wall resulting in partial or complete occlusion of the arterial lumen. "Our analysis demonstrated that cigarette smoke modulates expression of numerous lncRNAs in NREC including ZFAS1, which has been implicated in diverse diseases including mycobacterial infections, epilepsy, rheumatoid arthritis, atherosclerosis, and cancer." (PMID 40211119, 2025). "Circulating lncRNAs have become potential biomarkers of atherosclerosis in diagnostic, prognostic, and predictive tools, such as ZFAS1, HOTAIR, MALAT1." (PMID 37371830, 2023). "Recently, ZFAS1 was demonstrated to be related to the process of atherosclerosis and involved in regulating macrophage functions during the progression of atherosclerosis." (PMID 37418054, 2024). "m6A modifications of the lncRNA ZNFX1 Antisense RNA 1 (ZFAS1) and RAB22A, member RAS oncogene family (RAB22A) via METTL14 contributes to the development of atherosclerosis." (PMID 36482889, 2022). "Moreover, six lncRNAs, ZFAS1 (ZNFX1 antisense RNA 1), LOC100506730, LOC100506691, DOCK9-AS2, RP11-6I2.3, and LOC100130219, were confirmed as potential novel therapeutic and prognostic targets for atherosclerosis." (PMID 34421622, 2021). "Moreover, a few lncRNAs, such as ZFAS1, LOC100506730, LOC100506691, DOCK9-AS2, RP11-6I2.3, LOC100130219, were confirmed as important lncRNAs in atherosclerosis." (PMID 30873207, 2019). "Moreover, ZFAS1, LOC100506730, LOC100506691, DOCK9-AS2, RP11-6I2.3, and LOC100130219 were identified as key lncRNAs in atherosclerosis." (PMID 30873207, 2019). "A few lncRNAs, such as ZFAS1, LOC100506730, LOC100506691, DOCK9-AS2, RP11-6I2.3, LOC100130219, LOC100268168, DAPK1-IT1, LOC100507250, and LOC102723845, were confirmed as important lncRNAs due to that they co-expressed with more than 100 different mRNAs in Atherosclerosis." (PMID 30873207, 2019).
melanoma (8 papers, 2017 to 2025). A malignant, usually aggressive tumor composed of atypical, neoplastic melanocytes. "Specifically, in melanoma, knockdown of ZFAS1 was shown to reduces migration, invasion, and the markers of epithelial-mesenchymal transition." (PMID 33041669, 2020). "Another study has suggested that miR-150-5p had a downstream target relationship with ZFAS1 in the regulation of melanoma malignancy." (PMID 31827400, 2019). "While its antiviral functions may not be relevant to the progression of human tumors, its antisense lncRNA ZFAS1 (zinc finger antisense 1) is well known for promoting growth of melanoma and other tumors." (PMID 33041669, 2020). "Then, knockdown of ZFAS1 by siRNAs suppressed melanoma cell line proliferation." (PMID 30186041, 2018). "High Zfas1 expression has been proven as an unfavorable prognostic biomarker for many types of cancers; however, in melanoma it has not yet been described." (PMID 31231466, 2019).
rheumatoid arthritis (8 papers, 2017 to 2025). A chronic, systemic autoimmune disorder characterized by inflammation in the synovial membranes and articular surfaces. "This study aimed to evaluate the association of four lncRNAs (ANRIL, lnc-DC, MALAT1, ZFAS1) genes single nucleotide polymorphisms (SNPs) with susceptibility to rheumatoid arthritis (RA) patients, as well as their expression levels." (PMID 31736958, 2019). "ZFAS1 was found to increase inflammation and hyperplasia of fibroblast-like synoviocytes in rheumatoid arthritis and aggravates spinal cord injury by facilitating cell apoptosis and inflammatory." (PMID 36561842, 2022). "As previously reported, ZFAS1 depletion mitigates rheumatoid arthritis-like symptoms via miR-296-5p-dependent suppression of MMP-15." (PMID 36561842, 2022). "The authors report on a study that evaluated the association of four long noncoding RNA (lncRNA) (ANRIL, lnc-DC, MALAT1, ZFAS1) gene single-nucleotide polymorphisms (SNPs) with susceptibility to rheumatoid arthritis (RA) patients, as well as their expression levels." (PMID 34956240, 2021). "In rheumatoid arthritis (RA) patients, ZFAS1 expression was increased in synovial tissue and fibroblast-like synoviocytes (FLS) compared with that in healthy donors, and silence of ZFAS1 suppressed RA-FLS migration and invasion." (PMID 29262629, 2017).
diabetes (6 papers, 2016 to 2024). "Considering that STZ-induced diabetic mouse is a well-recognized animal model of diabetic retinopathy, we next investigated the effects of ZFAS1/miR-7-5p/ACSL4 axis on endothelial ferroptosis using the STZ mouse model." (PMID 36092160, 2022). "We further examined the interactions between ZFAS1 and miR-9 in mediating cardiac fibrosis in diabetes." (PMID 36240130, 2022). "However, the biological function and molecular mechanisms of ZFAS1 in diabetes remained unclear." (PMID 36240130, 2022). "We have studied the ncRNAs ZFAS1, MALAT1, miR-9, miR-146a and miR-200b in the context of diabetes and hyperglycemia-induced EndMT." (PMID 37924123, 2023). "Neither ZFAS1 nor CDR1AS was correlated with diabetes mellitus, hypertension, smoking history, or cardiac contractile and electrophysiological functions." (PMID 26928231, 2016).